CLEC4A (C-type lectin domain family 4 member A)
Description:
C-type lectin receptor that binds carbohydrates mannose and fucose but also weakly interacts with N-acetylglucosamine (GlcNAc) in a Ca(2+)-dependent manner. Involved in regulating immune reactivity. Once triggered by antigen, it is internalized by clathrin-dependent endocytosis and delivers its antigenic cargo into the antigen presentation pathway resulting in cross-priming of CD8(+) T cells. This cross-presentation and cross-priming are enhanced by TLR7 and TLR8 agonists with increased expansion of the CD8(+) T cells, high production of IFNG and TNF with reduced levels of IL4, IL5 and IL13. In plasmacytoid dendritic cells, inhibits TLR9-mediated IFNA and TNF production. May be involved via its ITIM motif (immunoreceptor tyrosine-based inhibitory motifs) in the inhibition of B-cell-receptor-mediated calcium mobilization and protein tyrosine phosphorylation. (Microbial infection) Involved in the interaction between HIV-1 virus and dendritic cells. Enhances HIV-1 binding/entry and virus infection. Requires ITIM motif-associated signal transduction pathway involving phosphatases PTPN6 and PTPN11, SYK, Src kinases and MAP kinases.
Synonyms: CD367; CLECSF6; DCIR; LLIR; HDCGC13P; DDB27; hDCIR
Tractability: Antibody: UniProt places it where antibodies can reach, with high confidence; its Gene Ontology location is reachable by antibodies, with high confidence; UniProt predicts a signal peptide or a membrane-spanning region. PROTAC: its protein half-life has been measured.
Gene: Protein-coding gene on chromosome 12 (8,123,617 to 8,138,607, forward strand). Ensembl gene ENSG00000111729.
Subcellular location: Cell membrane
Pathways (Reactome):
Immune System: Dectin-2 family
Gene Ontology:
Molecular function: calcium ion binding; carbohydrate binding; D-mannose binding; pattern recognition receptor activity; transmembrane signaling receptor activity
Biological process: antigen processing and presentation of exogenous peptide antigen via MHC class I; CD8-positive, alpha-beta T cell activation; negative regulation of cytokine production; negative regulation of tumor necrosis factor production; plasmacytoid dendritic cell antigen processing and presentation; antifungal innate immune response; cell adhesion; cell surface receptor signaling pathway
Cellular component: plasma membrane; external side of plasma membrane
Genetic constraint (gnomAD): Loss-of-function variants: 12 observed, 17.91 expected, observed/expected ratio (o/e) 0.67, 90% interval 0.43 to 1.09. The upper end of that interval is the gene's LOEUF score, 1.09, which puts it in group 4 of 6, group 1 being the genes least tolerant of losing a copy. Missense variants: 171 observed, 183.7 expected, observed/expected ratio (o/e) 0.93, 90% interval 0.82 to 1.06. Synonymous variants: 55 observed, 65.26 expected, observed/expected ratio (o/e) 0.84, 90% interval 0.68 to 1.05.
Homologues: Orthologues: chimpanzee CLEC4A (99% identical), macaque CLEC4A (89% identical), rabbit CLEC4A (67% identical), mouse Clec4a1 (52% identical), rat Clec4a1 (51% identical), tropical clawed frog clec4m (22% identical), zebrafish asgr1a (22% identical), zebrafish asgrl1 (22% identical), tropical clawed frog clec4e (20% identical), tropical clawed frog asgr1 (20% identical), zebrafish asgr1c.2 (19% identical), Drosophila melanogaster tfc (19% identical), and 14 more. Paralogues in human: CLEC4C (42% identical), CLEC6A (37% identical), CLEC4E (32% identical), CLEC4D (30% identical), ASGR1 (27% identical), CLEC10A (27% identical), ASGR2 (26% identical), CLEC4M (25% identical), CLEC4G (24% identical), CD209 (24% identical), CLEC17A (21% identical), FCER2 (21% identical), and 2 more.